POLR2J4 (RNA polymerase II subunit J4 (pseudogene) )
Synonyms: RPB11-phi; RASA4P; RASA4CP
Gene: Long non-coding RNA gene on chromosome 7 (43,940,895 to 44,040,670, reverse strand). Ensembl gene ENSG00000290758.
Diseases named in the same sentence as POLR2J4 in open-access papers:
POLR2J4 is named in the same sentence as 9 diseases in open-access papers, as found by Europe PMC text mining. Sharing a sentence is not in itself a finding about the gene and the disease. The quoted sentences say what the papers report.
hepatocellular carcinoma (5 papers, 2020 to 2024). A malignant tumor that arises from hepatocytes. "POLR2J4 is a non‐coding RNA and has recently been shown to be associated with survival in hepatocellular carcinoma by two independent studies." (PMID 34319007, 2021). "POLR2J4 has been reported as a composition of signature to predict the survival of cirrhotic hepatocellular carcinoma and recurrence-free hepatocellular carcinoma." (PMID 34194477, 2021). "POLR2J4 has also been used to predict recurrence-free survival in hepatocellular carcinoma." (PMID 32190687, 2020). "POLR2J4 functioned as an oncogene in colorectal through the microRNA-203a-3p.1 and CREB1 axis and is highly expressed in hepatocellular carcinomas." (PMID 36065303, 2022).
glioma (2 papers, 2022 to 2025). A benign or malignant brain and spinal cord tumor that arises from glial cells (astrocytes, oligodendrocytes, ependymal cells). "EdU incorporation assays revealed that POLR2J4 knockdown significantly impaired glioma cell proliferation, which was further exacerbated by CDDP exposure." (PMID 40661083, 2025). "Functional assays confirmed that POLR2J4 promotes glioma proliferation, migration, and cisplatin resistance." (PMID 40661083, 2025). "Functional assays revealed that POLR2J4 knockdown in glioma cell lines significantly reduced cell proliferation and DNA synthesis, as evidenced by EdU assays, and suppressed both migration and invasion capabilities, as shown by Transwell assays." (PMID 40661083, 2025). "We demonstrated that POLR2J4 promotes glioma cell proliferation, migration, and resistance to cisplatin both in vitro and in vivo." (PMID 40661083, 2025). "For instance, high expression of POLR2J4 has been reported to be associated with poor prognosis in various malignancies, while SNHG16 promotes glioma tumorigenesis via activation of the PI3K/AKT pathway and the miR-373/EGFR axis." (PMID 40661083, 2025). "Third, while our EdU, Transwell, CCK-8, and xenograft assays confirmed that POLR2J4 promotes glioma proliferation, migration, and chemoresistance, the molecular mechanisms—such as its regulation of PI3K–Akt signaling or immune checkpoints—remain to be elucidated." (PMID 40661083, 2025). "The results revealed that AL590666.2, POLR2J4, SNHG16, AL359541.1, AC004943.2, and SOX21-AS1 were significantly upregulated in glioma tissues compared to normal tissues." (PMID 40661083, 2025). "Compared to normal tissues, the expression levels of AL590666.2, POLR2J4, SNHG16, AL359541.1, AC004943.2, and SOX21-AS1 were significantly upregulated in glioma tissues." (PMID 40661083, 2025). "Finally, the expression levels of AL590666.2, POLR2J4, SNHG16, AL359541.1, AC004943.2, and SOX21-AS1 were significantly elevated in glioma cell lines compared to corresponding normal cell lines." (PMID 40661083, 2025).
Cirrhosis (1 paper, 2024). A chronic disorder of the liver in which liver tissue becomes scarred and is partially replaced by regenerative nodules and fibrotic tissue resulting in loss of liver function. "A higher POLR2J4 level was closely associated with the presence of cirrhosis (P = .029), higher AFP (P < .001), advanced Edmondson grade (P = .034), TNM stage (P = .031), and the presence of vascular invasion (P = .022) in HBV–HCC patients." (PMID 39412398, 2024).
liver cancer (1 paper, 2019). An epithelial or non-epithelial malignant neoplasm that arises from the liver. "Among the four lncRNAs, AC093797.1 and POLR2J4 were risk factors for liver cancer, whereas the other two were protective factors (AL121748.1 and AL162231.4)." (PMID 31396449, 2019). "With the exception of POLR2J4, the lncRNAs were deemed prognostic markers of liver cancer for the first time, to our knowledge." (PMID 31396449, 2019).
liver diseases (1 paper, 2024). "Including a group of control individuals with other etiologies of HCC or liver diseases would help interpret the significance of POLR2J4 more deeply." (PMID 39412398, 2024).
tumor (3 papers, 2020 to 2025). "Immunohistochemical staining of tumor sections demonstrated that POLR2J4 knockdown markedly reduced the expression of TGF-β1 and PD-L1 compared to controls." (PMID 40661083, 2025). "POLR2J4 acted as a prognostic biomarker and a tumor promoter of HBV–HCC by modulating miR-214-3p." (PMID 39412398, 2024). "Silencing POLR2J4 was found to suppress cell growth, migration, and invasion, suggesting that POLR2J4 could serve as a tumor promoter in the progression of HBV–HCC." (PMID 39412398, 2024). "In the tissue samples, POLR2J4 was significantly upregulated in the tumor tissues (P < .001)." (PMID 39412398, 2024). "Additionally, the present study focused on comparing the expression of POLR2J4 in tumor lesions and adjacent normal tissues." (PMID 39412398, 2024). "Thus, POLR2J4 could act as both a prognostic biomarker and a tumor promoter by regulating miR-214-3p." (PMID 39412398, 2024). "miR-214-3p, predicted to bind with POLR2J4, showed significant downregulation in HBV–HCC tumor tissues and cells compared to normal tissues, cells, and non-HBV cells (P < .001)." (PMID 39412398, 2024). "In tumor tissues of HBV–HCC patients, there was an observed increase in the expression of POLR2J4." (PMID 39412398, 2024). "Mechanistically, POLR2J4 knockdown reduced the expression of drug resistance genes (ABCB1, ABCC1, BCL2), decreased serum levels of IL-6 and TGF-β1, and downregulated TGF-β1 and PD-L1 in tumor tissues, highlighting its role in establishing an immunosuppressive, drug-resistant microenvironment." (PMID 40661083, 2025). "POLR2J4 and miR-214-3p were predicted to bind with each other, and a significant negative correlation was observed between the expression of POLR2J4 and miR-214-3p in HBV-induced HCC tumor tissues." (PMID 39412398, 2024). "They demonstrated that MSC-AS1, POLR2J4, EIF3J-AS1, SERHL, RMST, and PVT1 were significantly upregulated in tumor samples compared to nontumor samples and were significantly associated with RFS." (PMID 33520012, 2020).
cancer (2 papers, 2020 to 2024). A tumor composed of atypical neoplastic, often pleomorphic cells that invade other tissues. "Besides some well-known cancer-associated lncRNAs such as LINC01158, LINC00461, XIST, and HOTAIRM1, we also identified several potential GBM progression-associated lncRNAs like POLR2J4, WWTR1-AS1, and VIM-AS1." (PMID 33505440, 2020).
POLR2J4 also shares sentences with these, for which no sentence is quoted: colorectal cancer (1 paper); retinoblastoma (1).